MUC1 (mucin 1, cell surface associated)
Diseases named in the same sentence as MUC1 in open-access papers (continued):
Sharing a sentence is not in itself a finding about the gene and the disease.
breast carcinoma (continued). "This is consistent with previous studies on breast cancer, showing that MUC1 influences cell proliferation by inducing EGF receptor (EGFR) nuclear translocation and increasing its binding affinity with the cyclin D1 gene promoter." (PMID 38254882, 2024). "These nanoparticles were modified with the S2.2 aptamer to specifically deliver PTX to MCF-7 breast cancer cells, which overexpress the MUC1 protein on their surface." (PMID 38675202, 2024). "CEA, a glycoprotein involved in cell adhesion, can be elevated in various cancers, while CA15-3, a protein antigen of the transmembrane glycoprotein MUC-1, increases in higher breast cancer stages." (PMID 38672729, 2024). "In terms of resistance testing, mucin 1 (MUC1) is a potential target for overcoming Trastuzumab resistance in breast cancer therapy." (PMID 38338997, 2024). "We evaluated MUC1 mRNA expression in three breast cancer cell lines, i.e., MCF-7, MDA-MB-468, and MDA-MB-231, a normal human breast epithelial cell line, i.e., MCF-10A, and PBMCs derived from a healthy volunteer, respectively." (PMID 39886667, 2024). "S-palmitoylation of MUC1 modulates its recycling from endosomes to the plasma membrane, and the intracellular localization of MUC1 is altered during breast cancer metastasis." (PMID 38415253, 2024). "In breast cancer, MUC1 was connected to resistance to Her2 targeting therapy with MUC1-mediated glycoprotein signatures identified in brain metastases." (PMID 39767713, 2024). "This is manifested in the suppression of the anti-inflammatory activity of MUC1 due to pro-inflammatory cytokines that have passed the hematosalivary barrier and are activated by oncogenic processes occurring in breast cancer." (PMID 39456554, 2024). "The work describes a method for determining the protein marker of breast cancer MUC1 using an electrode coated with nanofibers, nanotubes, and gold nanoparticles with an attached aptamer that binds to MUC1." (PMID 38398911, 2024). "We have also not yet assessed the diagnostic and prognostic significance of changes in the level of salivary MUC1 in breast cancer." (PMID 39456554, 2024). "MUC1 is often overexpressed in breast cancer, correlating with cancer cell infiltration and migration." (PMID 38627939, 2024). "MUC-1 is one of the most widely used serum tumor biomarkers in women with breast cancer and recent studies suggest its promising potential in the diagnosis and treatment of CMTs." (PMID 38474142, 2024). "used biotinylated SERS nanotags to capture breast cancer CTCs on streptavidin coated micro-posts for a 5-plex SERS biosensing of MUC1, EpCAM, EGFR, HER2, and CD133." (PMID 38811455, 2024). "Initial experimental results demonstrate that the rAdF35-MUC1 achieves significantly enhanced infection efficiency and sensitivity in MUC1-positive breast cancer cells in vitro." (PMID 39886667, 2024). "MUC1 is a transmembrane glycoprotein that exhibits low or negligible expression in normal breast tissue but is markedly upregulated in breast cancer cells." (PMID 39886667, 2024). "CA153 is the product of MUC1 gene, and itshigh expression is usually associated with colon cancer, breast cancer, ovarian cancer, lung cancer, andpancreatic cancer." (PMID 38699697, 2024). "Another type of DNA vaccine that has been investigated is the MUC-1 vaccine, which was able to decrease tumor growth in mice bearing mammary cancer." (PMID 38474142, 2024). "Since MUC-1 is aberrantly glycosylated and overexpressed in more than 90% of mammary tumor cases, it is considered a favorable target for engineering CAR T cells." (PMID 38474142, 2024). "MUC1 is expressed in more than 90% of breast cancer samples, 25–70% of colon cancer samples, and 10–90% of other forms of cancer tissues." (PMID 37489369, 2023). "Mucin-1 (MUC1) is a transmembrane glycoprotein overexpressed in several solid tumors, such as breast cancer and melanoma." (PMID 38067178, 2023).
breast carcinoma (continued). "This is consistent with a previous study in breast cancer demonstrating that p-EGFR activates MUC1 by phosphorylating MUC1." (PMID 36810913, 2023). "Even though the small molecule apigenin was reported to inhibit MUC1-CT dimerisation in the breast cancer cell lines, the inhibitory effect was probably mediated by blocking other targets." (PMID 36810913, 2023). "NCT05812326 is a single-center, open-label, completed phase 1/2 trial evaluating the safety and efficacy of PD-1 gene knockout anti-MUC1 CAR-T cells (AJMUC1) in patients with advanced MUC1-positive breast cancer." (PMID 37371075, 2023). "MUC1 is a mucin glycoprotein overexpressed on some adenocarcinoma cells and is considered an important tumor surface marker, especially breast cancer." (PMID 37919282, 2023). "An inverted cytokine receptor composed of the IL-4 receptor exodomain fused to the IL-7 receptor endodomain improved the persistence and anti-tumor activity of anti-MUC1 CAR T-cells against an IL-4-secreting breast cancer CDX model." (PMID 38201551, 2023). "miR-125b, which is downregulated in breast cancer cells, also suppresses translation of the MUC1 oncoprotein, while miR-23a is considered to be involved in TNF-α-induced endothelial cell apoptosis." (PMID 37958720, 2023). "For instance, AuNPs act as multivalent carriers for loading the MUC1 glycopeptide antigen and α-galactosylceramide immune adjuvant to develop vaccines for treating breast cancer." (PMID 37514054, 2023). "In breast cancer cells there is increased sialylation of MUC1, which results in truncation of sugar branches that would be otherwise elongated." (PMID 37455827, 2023). "We explored the expression of MUC1 using Sangerbox tools and found that MUC1 expression was higher in breast cancer tissues than in normal tissues." (PMID 36895039, 2023). "Correlation of the cellular localization of MUC1 with breast cancer prognosis was first reported by Ceriani and co-workers using mAb BrE-39." (PMID 37002293, 2023). "MUC1 is a possible antigen to be utilized as a site-specific target for the deployment of therapeutic agents as a vaccine against MUC1 for breast carcinoma." (PMID 37513835, 2023). "Aberrant glycoforms of MUC1 have been evaluated in order to be used as breast cancer biomarkers with improved clinical performance over the conventional CA15-3 and CA27.29 assays." (PMID 37455827, 2023). "Another promising CAR T cell target is Mucin1 (MUC1), an aberrantly glycosylated protein expressed in the majority of breast cancer cases." (PMID 37173782, 2023). "In clinical studies on women with Stage I and Stage II breast cancer, MUC-1 IgG and IgM antibodies were tested and assessed for their association with disease-specific survival." (PMID 37513835, 2023). "Surprisingly, we found that MUC1 is the binding protein of MAL2 in breast cancer cells by reviewing the literature." (PMID 36895039, 2023). "An antibody-lectin sandwich assay was designed to detect the aberrant glycosylation of MUC1 in sera from breast cancer patients, using an antibody to capture the protein and the lectin Con A to detect high mannose N-glycans present in MUC1." (PMID 37455827, 2023). "MUC-1 is proposed as a potential biomarker to be targeted in breast cancer therapy because patients would typically overexpress the MUC-1 biomarker (approximately 90%) for immune system detection." (PMID 37513835, 2023). "The pioneered MUC-1 peptide vaccine study was performed in 1995 against patients with breast carcinoma." (PMID 37513835, 2023). "The specificity of MUC1 for surface receptors of breast cancer cells rendered AuNP-mediated drug delivery 96% more efficient." (PMID 37514054, 2023).
breast carcinoma (continued). "The C-terminal subunit of MUC1 (MUC1-C) is involved in multiple biological processes in breast cancer and is considered an oncoprotein." (PMID 36895039, 2023). "In one report, MUC1-modified PEG-AuNPs successfully delivered paclitaxel precisely to breast cancer cells." (PMID 37514054, 2023). "Cellular localization patterns of MUC1 in breast cancer were previously reported to differ depending on the type of tumor and the use of mAbs with different specificities." (PMID 37002293, 2023). "Anti-MUC1 allogeneic CAR-T cells are in phase 1 clinical trial for various solid tumors including breast cancer (NCT05239143)." (PMID 37173782, 2023). "In a phase III trial, vaccination of breast cancer patients with oxidized mannan-MUC1 resulted in significantly lower recurrence rates than placebo." (PMID 37007133, 2023). "A pilot Phase III analysis of 31 early Stage II breast cancer patients utilizing oxidized mannan-MUC-1 immunotherapy found that MUC1 immunotherapy is effective." (PMID 37513835, 2023). "GALNT1 initiates O-glycosylation of glycoproteins; Sonic hedgehog protein (Shh), osteopontin, and MUC1, which contributes to the generation of breast cancer." (PMID 37444599, 2023). "MUC1 extracellular domain was reported to contribute to a decrease in the immune response in breast cancer cells." (PMID 37160910, 2023). "The expression of MAL is significantly down-regulated, and it plays an important role as a binding gene of MUC1 in breast cancer." (PMID 36059531, 2022). "Because MUC1 is expressed in the majority of epithelial-derived solid tumors, such as breasts cancer subtypes, MUC28z CAR T-cells will most likely have extensive applicability for solid tumor targeting." (PMID 36153626, 2022). "For example, miR-145 negatively regulates MUC1 and suppresses invasion and metastasis of breast cancer cells, and miR-145 suppresses proliferation, metastasis, and EMT of colorectal cancer via suppressing the EGFR-associated signaling pathway." (PMID 35847793, 2022). "MUC1 has been shown to be overexpressed in a variety of epithelial cancers, including breast cancer." (PMID 35568869, 2022). "MUC1 is aberrantly overexpressed in numerous human carcinomas, including in greater than 90% of breast cancer cases." (PMID 36289190, 2022). "Although a higher titer of circulatory anti-MUC-1 antibodies was found in humans with breast cancer, to the best of our knowledge, the first and only study on autoantibodies against MUC-1 in canines was recently conducted in 2018." (PMID 35000604, 2022). "MUC1 is a heterodimeric surface protein aberrantly overexpressed in more than 90% of breast cancers." (PMID 35468841, 2022). "Our investigation into how MUC1 protects cancer cells from drug transportation provides a physiologically relevant context to understand the reason of the high expression of MUC1 in breast cancer cells." (PMID 35970845, 2022). "Many studies have looked at the HER family, mesothelin (Meso), folate receptor alpha (FR‐α), NKG2D ligands, c‐MET, and mucin 1 (Muc1) as potential targets for breast cancer in vitro and in animal models that will be discussed in the following sections." (PMID 35762299, 2022). "The identification of specific and sensitive molecular biomarkers involved in breast cancer has a consequential clinical significance; hence, MUC-1 has been broadly investigated for the treatment of HBC." (PMID 35000604, 2022). "AS1402, a humanized immunoglobin monoclonal antibody binding to the MUC1-N tandem, showed antibody-dependent cytotoxicity against MUC-1-positive breast cancer cells in a phase I trial." (PMID 35389164, 2022). "HER2, an antigen that is expressed in large quantities in breast cancer, and is similar to MUC1 and CEA, was also found to be overexpressed in premalignancy stages of breast cancer." (PMID 36298592, 2022). "MUC1 (also known as CA 15.3) is a transmembrane mucin, a glycoprotein with O-glycosylated tandem repeats, overexpressed in cancer, in particular in breast cancer." (PMID 35380164, 2022).
breast carcinoma (continued). "The investigators propose to evaluate safety and preliminary antitumor activity in patients with metastatic MUC1*-positive breast cancer." (PMID 35158915, 2022). "MSNs can bind the drug EPI and mucin 1 (MUC1) aptamer, demonstrating that MSNs-MUC1-EPI has targeted delivery and a therapeutic effect on MUC1-positive breast cancer cells." (PMID 36559056, 2022). "Further investigations in the modification of CAR T cell to overcome suppressive elements in the tumor milieu should also be addressed to improve efficacy and safety of CAR MUC1 T cells for breast cancer treatment." (PMID 36457849, 2022). "Study in estrogen-receptor positive (ER+) human breast cancer have revealed that estrogen receptor α (ER α) resides in estrogen-responsive elements of the MUC1 promoter and triggers MUC1 transcription." (PMID 35000604, 2022). "Epigallocatechin gallate (EGCG) can inhibit the production of MUC1 and thereby suppress breast cancer metastasis." (PMID 35216622, 2022). "Our group developed a novel TLR7 agonist-conjugated MUC1 peptide vaccine that elicited effective immune responses and robust antitumor effects in a mouse breast cancer model." (PMID 36499455, 2022). "It is also important to note that transmembrane C-terminal MUC1 (MUC1-c) is necessary for Tyr705-Stat3 phosphorylation in breast cancer cells and promotes Stat3-mediated transcription in an auto-inductive regulatory loop." (PMID 36017196, 2022). "In breast cancer, MUC1 is highly sialylated because of increased expression of α2,3-sialyltransferase." (PMID 36457849, 2022). "Our findings show that CAR T cell targeting MUC1 can be effective against MUC1+ breast cancer cell and support the further development of CAR MUC1 T cells containing 41BB signaling in preclinical and clinical studies of breast cancer treatment." (PMID 36457849, 2022). "We next assessed the ability of CAR MUC1 T cells to expand and control breast cancer cells in vitro." (PMID 36457849, 2022). "miR-1226 can directly target the 3′ UTR of MUC1 mRNA and downregulate endogenous MUC1 protein levels in human breast cancer cell lines, which can increase ROS, lower the mitochondrial transmembrane potential, and ultimately decrease cell survival." (PMID 35154471, 2022). "MUC1 is overexpressed in 91% of breast cancers and is often found in pancreatic cancer, colon cancer, and lung cancer." (PMID 36451832, 2022). "Nevertheless, it was unclear how MUC1 in breast cancer cells responds to the threat of chemotherapeutics." (PMID 35970845, 2022). "CAR MUC1 T cells showed high transduction efficiency and antigen specificity toward MUC1+ cancer cell lines and primary breast cancer cells." (PMID 36457849, 2022). "For example, MUC1 is the O-glycosylated protein prevalent in breast carcinoma, and the MUC1 lysate-pulsed DCs promote the expression of MUC1-specific CD8 + T cells in breast cancer immunotherapy." (PMID 35752750, 2022). "Mucin 1 (MUC1) has received increasing attention due to its high expression in breast cancer, in which MUC1 acts as a cancer antigen." (PMID 36499455, 2022). "Further studies in breast cancer xenograft mouse models are necessary to compare in vivo antitumor activity and in vivo persistence between anti-MUC-1 CAR T cells with a 4-1BB or CD-28 endosignaling domain." (PMID 36457849, 2022). "A systematic review of the literature revealed miR-145′s role in various hallmarks of cancer; for example, it suppresses cell invasion and metastasis in breast cancer cell lines by directly targeting mucin 1 (MUC1)." (PMID 36077665, 2022). "This nanoformulation was conjugated with an anti-MUC1 aptamer and was shown to efficiently bind to MUC1-overexpressing metastatic breast cancer cells." (PMID 35205658, 2022). "Mucin-1 (MUC1) is a type I transmembrane protein, uniformly overexpressed on breast cancer, and its expression serves as a predictive marker for metastatic progression and poor prognosis." (PMID 36457849, 2022).
breast carcinoma (continued). "Like MUC1, breast cancer patients with overexpressed GCNT3 and GALNT5 predict worse survival, probably due to the worse drug response mediated by over-glycosylation." (PMID 35970845, 2022). "In vitro validation was done using MUC1-negative HCC cell line HepG2, MUC1-positive HCC cell line SMMC-7721, and MUC1-positive breast cancer cell line MCF-7." (PMID 35248080, 2022). "One of these biomarkers is MUC1, which is overexpressed in many malignancies, particularly in breast cancer (BC)." (PMID 35406491, 2022). "The oncogenic MUC1 has been found overexpressed in breast cancer and commonly predicts worse prognosis in patients." (PMID 35970845, 2022). "For example, melanoma antigen ganglioside GD3 is expressed in most melanoma cells and mucin oncoprotein 1 (MUC1) is a glycoprotein that is overexpressed in most breast cancers." (PMID 36114560, 2022). "Soluble MUC1 has been discussed as a biomarker for predicting prognosis, treatment efficacy, and monitoring disease activity in breast cancer (BC) patients." (PMID 35406491, 2022). "Using LC-MS/MS analysis, we identified the mitochondrial protein ATAD3A that interacted with MUC1 in breast cancer cells." (PMID 36289190, 2022). "MUC1.TR2.4-1BB CAR-T cells showed increased cytotoxic activity against breast cancer tumors and inhibited tumor growth more effectively than either MUC1 CAR-T cells or TR2.4-1BB T cells." (PMID 35211124, 2022). "An ECL aptasensor that detects the expression of MUC1 protein in breast cancer cells and their derived exosomes gives full play to the advantages of both." (PMID 36235208, 2022). "The DC-targeted vaccine oxidized mannan-MUC-1 dramatically decreased the recurrence rate in 31 patients with breast cancer (12.5% vs. 60% in patients who received placebo) at 15 years of follow-up." (PMID 35148751, 2022). "MUC1 knockout (KO) markedly sensitized breast cancer cells to apigenin cytotoxicity in vitro and in vivo." (PMID 35970845, 2022). "The developed vaccine triggered a significant and durable antibody response, through specific binding of immunized serum to MUC1-expressing breast cancer cells." (PMID 35205658, 2022). "It was shown that the differentiation of breast cancer stem cells occurred by the knockdown of CD44 and caused the loss of the CSC phenotype along with the reduced expression of Bcl-2 and Muc-1 proteins, reducing metastasis and tumorigenesis." (PMID 35631686, 2022). "In a recent study, the breast cancer marker Mucin 1 was detected using a competitive electrochemical aptasensor fabricated on a cDNA-ferrocene/MXene probe (MUC1)." (PMID 35403935, 2022). "Next, we investigated the cytokine profile of CAR MUC1 T cells after exposure to MUC1-expressing breast cancer cells." (PMID 36457849, 2022). "MUC1-specific T cells and antibodies are also identified in breast cancer patients, and MUC1-specific immunity is beneficial in the treatment of breast cancer." (PMID 36499455, 2022). "GATA3, a factor acting as a MUC1 transcriptional regulator in breast cancer cells, was downregulated by ionizing radiation and the addition of melatonin did not modify its transcription." (PMID 35625825, 2022). "CCCP-induced mitophagy in MUC1-expressing cells was mitigated by the MUC1 inhibitor peptide GO203 compared with the control peptide CP2 in all four breast cancer-derived cell lines." (PMID 36289190, 2022). "A Phase I study of anti-MUC1 CAR-T cells for patients with advanced MUC1 positive breast cancer is currently recruiting (NCT04020575)." (PMID 36351947, 2022). "Recently, studies have developed antibody–drug conjugated (ADC) based on MUC1 employed in the treatment trastuzumab-resistant breast cancer patients." (PMID 35879749, 2022). "This study suggested that the liposomal DDA/MPLA with lipid-MUC1 is a promising antitumor vaccine, which can be used for the immunotherapy of various epithelial carcinomas represented by breast cancer." (PMID 35186882, 2022).